SOWAHA (sosondowah ankyrin repeat domain family member A)
Synonyms: ANKRD43
Tractability: Antibody: UniProt predicts a signal peptide or a membrane-spanning region.
Gene: Protein-coding gene on chromosome 5 (132,813,302 to 132,816,786, forward strand). Ensembl gene ENSG00000198944.
Genetic constraint (gnomAD): Loss-of-function variants: 17 observed, 14.71 expected, observed/expected ratio (o/e) 1.16, 90% interval 0.79 to 1.7. The synonymous counts are far from expectation, so gnomAD's model fits this gene poorly and the ratio says little. Missense variants: 862 observed, 636.75 expected, observed/expected ratio (o/e) 1.35, 90% interval 1.28 to 1.43. Synonymous variants: 420 observed, 305.2 expected, observed/expected ratio (o/e) 1.38, 90% interval 1.27 to 1.49.
Homologues: Orthologues: chimpanzee SOWAHA (99% identical), macaque SOWAHA (96% identical), chimpanzee SOWAHA (94% identical), pig SOWAHA (81% identical), dog SOWAHA (77% identical), mouse Sowaha (77% identical), rat Sowaha (74% identical), tropical clawed frog sowaha (33% identical), zebrafish sowahab (26% identical), zebrafish sowahaa (17% identical). Paralogues in human: SOWAHB (28% identical), SOWAHC (21% identical), SOWAHD (15% identical).
Diseases named in the same sentence as SOWAHA in open-access papers:
SOWAHA is named in the same sentence as 4 diseases in open-access papers, as found by Europe PMC text mining. Sharing a sentence is not in itself a finding about the gene and the disease. The quoted sentences say what the papers report.
melanoma (1 paper, 2021). A malignant, usually aggressive tumor composed of atypical, neoplastic melanocytes. "During development, the expression of murine SOWAHA is observed in the postmitotic mantle zone during the specification and patterning of progenitor cells and it is significantly downregulated by the exposure of nonsteroidal anti-inflammatory drugs to the canine melanoma cell line." (PMID 33152230, 2021).
cancer (2 papers, 2022 to 2025). A tumor composed of atypical neoplastic, often pleomorphic cells that invade other tissues. "Additionally, SOWAHA (ANKRD43) has emerged as a potential tumor suppressor, with reduced expression linked to worse outcomes in several cancers, including EC." (PMID 40805172, 2025).
SOWAHA also shares sentences with these, for which no sentence is quoted: glioma (1 paper); tumor (1).